EEF1A1 (eukaryotic translation elongation factor 1 alpha 1)
Diseases named in the same sentence as EEF1A1 in open-access papers (continued):
Sharing a sentence is not in itself a finding about the gene and the disease.
meningioma (1 paper, 2021). A generally slow growing tumor attached to the dura mater. "Overall, WHO grade 1 meningiomas harbored numerous and heterogeneous genetic variants, which most frequently affected the NF2 (47%) gene and to a less extent the PNMA6A (22%), TIGD1 (16%), SMO (13%), PTEN (13%), CREG2 (9%), EEF1A1 (6%), POLR2A (6%), ARID1B (3%), and FAIM3 (3%) genes." (PMID 34868937, 2021). "Another four genes (PNMA6A, TIGD1, PTEN, and SMO) were found to be altered in >10% of all WHO grade 1 meningiomas investigated, while the remaining CREG2, EEF1A1, and POLR2A genes were recurrently altered in a minority (<10%) of cases." (PMID 34868937, 2021).
metastatic prostate carcinoma (1 paper, 2012). A carcinoma that arises from the prostate gland and has spread to other anatomic sites. "Thus, immunohistochemical (IHC) staining for eEF1A1 was performed using clinical tissue material from patients with BPH, organ confined cancer, and bone from patients both with and without metastatic prostate cancer." (PMID 22355332, 2012).
myocardial infarction (1 paper, 2011). Gross necrosis of the myocardium, as a result of interruption of the blood supply to the area, as in coronary thrombosis. "Gapdh, Polr2a and Actb consistently showed the highest gene expression variability and the expression levels of Gapdh, Polr2a, Actb, B2m and Eef1a1 were found to be selectively up- or downregulated after myocardial infarction." (PMID 21858224, 2011). "We furthermore caution against the use of Gapdh, Polr2a, Actb, B2m and Eef1a1 for gene expression normalization in myocardial infarction studies because of selective up- or downregulation after myocardial infarction." (PMID 21858224, 2011). "We furthermore caution against the use of Gapdh, Polr2a, Actb, B2m and Eef1a1 for gene expression normalization in myocardial infarction studies because of selective up- or downregulation after myocardial infarction, which could potentially lead to biased study outcomes." (PMID 21858224, 2011).
myopia (1 paper, 2024). "According to our research, patients with pathologic myopia had downregulated expression of XYLT1, VCAN, and SPOCK2 and upregulated expression of TUBA1A and EEF1A1." (PMID 39160465, 2024).
Nephropathy (1 paper, 2025). A nonspecific term referring to disease or damage of the kidneys. "This deposition was further enhanced in the OE-eEF1A1 group, indicating that eEF1A1 overexpression may promote immune complex-mediated nephropathy." (PMID 41262540, 2025).
oligodendroglioma (1 paper, 2018). A well-differentiated (WHO grade II), diffusely infiltrating neuroglial tumor, typically located in the cerebral hemispheres. "In Bredel’s dataset, two analyses showed that EEF1A1 mRNA levels were significantly upregulated in anaplastic dendroglioma and oligodendroglioma." (PMID 29342219, 2018).
ovarian clear cell adenocarcinoma (1 paper, 2018). A malignant glandular epithelial neoplasm characterized by the presence of clear and hobnail cells. "While EEF1A1 was found to be downregulated in ovarian serous surface papillary carcinoma in Welsh’s dataset, EEF1A2 was upregulated in ovarian clear cell adenocarcinoma in Hendrix’s dataset." (PMID 29342219, 2018).
pancreatic adenocarcinoma (1 paper, 2024). "Also, high expression of EEF1A2 is associated with poor prognosis, but the TCGA dataset (PAAD) from GEPIA2 showed a negative hazard ratio for EEF1A2 and EEF1A1 in pancreatic adenocarcinoma." (PMID 38172654, 2024).
pheochromocytoma (1 paper, 2016). "A study of pheochromocytoma cells also showed that stimulation with a nerve growth factor causes preferential synthesis of eEF1A1 over eEF1A2." (PMID 26981313, 2016).
phyllodes tumor (1 paper, 2018). A benign, borderline, or malignant fibroepithelial neoplasm arising from the breast and rarely the prostate gland. "Notably, one of these three reports studied benign neoplasms and another involved phyllodes tumors, which may be benign or malignant, indicating that EEF1A1 mRNA is typically underexpressed in malignant breast cancer." (PMID 30224719, 2018).
prostate adenocarcinoma (1 paper, 2012). "The expression of EEF1A2 and EEF1A1 genes were analysed in four Finefix-fixed paraffin-embedded samples referred to four patients with a clinical diagnosis of prostate adenocarcinoma." (PMID 22095224, 2012). "In prostate adenocarcinoma, the dissection of the expression behaviour of the eukaryotic elongation factors (eEF1A1/2) has not yet fully elucidated." (PMID 22095224, 2012).
squamous cell carcinoma (1 paper, 2015). A carcinoma arising from squamous epithelial cells. "EEF1A1 is known to be ubiquitously expressed and has been described as a useful reference gene for real-time PCR analysis in colon and other human tissues e.g. in myocardium, in cervical tissue as well as in normal lung and lung squamous-cell carcinoma tissue." (PMID 26222051, 2015).
cancer (97 papers, 2008 to 2026). A tumor composed of atypical neoplastic, often pleomorphic cells that invade other tissues. "In cancer research, eEF1A1 and eEF1A2 proteins have been proposed as possible hallmarks for cell transformation and tumour progression." (PMID 35456960, 2022). "This is consistent with the observation that increased expression of EEF1A1 is associated with sensitivity to olaparib in the independent GDSC pan-cancer cell lines." (PMID 33803939, 2021). "EEF1A1 mRNA expression was associated with increased sensitivity to olaparib in the GDSC pan-cancer cell lines and found to be highly expressed in olaparib-sensitive HGSOC cell lines, including BRCA2-mutated cell line OV4453, compared to resistant cell lines." (PMID 33803939, 2021). "In our previous study, we have compared the expression of eEF1A1, a well-characterized actin-binding protein associated with the invasiveness of cancer cells, in this panel of cell lines." (PMID 29547514, 2018). "Encoded by EEF1A1, the eukaryotic translation elongation factor eEF1α1 strongly promotes the heat shock response, which protects cancer cells from proteotoxic stress, following for instance oxidative stress, hypoxia or aneuploidy." (PMID 30224719, 2018). "Given that aberrant eEF1A1 activities have been implicated in a number of cancers and the translation machinery represents an important area of oncology research, our findings suggest new possibilities for combinatorial therapeutic approaches." (PMID 28678185, 2017). "Although overexpression of EEF1A1 in the liver enhances tumor progression, the mechanism behind the high-risk (hazard ratio = 3.8, p = 0.002) EEF1A1-432 hotspot in liver hepatocellular carcinoma, or any other cancer, remains unexplored." (PMID 38473427, 2024). "While analyzing multiple cancer disorders, we found highly variable expression among genes implicated in cancer: EEF1A1, GNAS, NPM1, PIM1, and RHOA are known oncogenes; H3F3A, PTPRC, SMARCB1, and B2M are possible oncogenes; and CASP8, JAK1, and PRKAR1A are known tumor suppressor genes." (PMID 34174938, 2021). "For example, the truncated variants of EEF1A1 promote or suppress cancer cells." (PMID 34067398, 2021). "The protein EEF1A1, containing missense mutation in OS patients, shows interaction with hsa-miR-342-3p, known to regulate variety of oncogenic processes, including cellular proliferation in different cancers." (PMID 28824643, 2017). "Therefore, targeting these differences holds significant promise in that selective eEF1A2 inhibition could treat the neurological disorders caused by EEF1A2 mutations while sparing normal tissues, whereas eEF1A1-specific compounds might address cancers with oxidative stress vulnerabilities." (PMID 40806463, 2025). "Our study showed that Eef1a1 promotes the proliferation of myoblasts, consistent with its regulatory role in promoting proliferation observed in cancer cells." (PMID 38732031, 2024). "The canonical function carried out by EEF1A2 in cells is redundant with the activities of the other EEF1A isoform, EEF1A1, which is also a promising candidate for targeting cancers." (PMID 38172654, 2024). "Eukaryotic translation elongation factor 1 alpha 1 (EEF1A1) have been proved to play important roles in various human cancers, whereas the deubiquitination of EEF1A1 was poorly understood." (PMID 38965582, 2024). "Biological evaluation discovered 29, one of these rationally designed eEF1A1 inhibitors, with optimal inhibitory activity against several cancer cell lines but low toxicity toward a normal cell line." (PMID 36982256, 2023). "The existence of multiple pseudogenes for EEF1A1 in humans was previously observed, and their expression was found to be correlated with various diseases, mostly different types of cancers." (PMID 36614310, 2023).
cancer (continued). "Our data show that the eEF1A1 protein is significantly overexpressed in Gleason ≥7; the highest expression was found in locally undifferentiated cancer cells." (PMID 35456960, 2022). "The ability of GT75 to co-localise with the fraction of eEF1A1 bound to actin in the cytoskeleton suggests that the eEF1A1–actin complex plays a role in cancer cell maintenance." (PMID 35456960, 2022). "Overexpression of eEF1A1 and eEF1A2 was related to a few different cancer types, such as plasmacytomas, HCC, clear cell renal cell carcinoma, breast cancer, gastric cancer, prostate cancer, ovarian cancer and CRC." (PMID 36387239, 2022). "eEF1A1 has multiple regulatory functions during cancer progression, including modulating the cytoskeleton, exhibiting chaperone-like activity, and regulating cell proliferation and cell death." (PMID 33809929, 2021). "Aberrantly upregulated eEF1A1 has been detected in many tumor tissues and overexpression of eEF1A1 is related to cancer cell proliferation, invasion, and migration." (PMID 33221755, 2020). "The gene EEF1A1 also plays a key role on the proliferation inhibition and apoptosis induction of human acute T lymphocytic leukemia cells, contributing to cancer survival in haematopoietic malignancies." (PMID 30753220, 2019). "EEF1A1 was a biomarker used to distinguish between cancer and normal tissue in our previous study, using a neural network-based feature selection algorithm." (PMID 31703307, 2019). "For stage II cancer, the 5-year OS of patients with high EEF1A1 expression tended to be longer than that of patients with low EEF1A1 expression (89.0% vs. 71.1%, p = 0.051, HR = 2.68, 95% CI = 0.96–7.43)." (PMID 31703307, 2019). "For stage III cancer, the 5-year OS was 88.1% for patients with high EEF1A1 expression and 62.6% for those with low EEF1A1 (p = 0.030, HR = 2.22, 95% CI = 1.06–4.50)." (PMID 31703307, 2019). "Higher expression of EEF1A2, EEF1B2, EEF1G, EEF1D, EEF1E1 and EEF2 was observed in most of the cancer types, whereas reverse trend was observed for EEF1A1." (PMID 29342219, 2018). "Univariate and multivariate analyses indicate that EEF1A1 mRNA underexpression independently predicts poor patient prognosis for estrogen receptor-positive (ER+) cancers." (PMID 30224719, 2018). "For EEF1A1 expression, a total of 30 studies showed statistically significant difference between tumor and normal samples, across all cancer types." (PMID 29342219, 2018). "Given that deregulated mRNA translation is a frequent feature of cancer and that eEF1A1 is highly expressed in many human tumours, these findings present new possibilities for the therapeutic targeting of EZH2 in AML." (PMID 28678185, 2017). "Overexpression of eEF1A1 was used to assay its function in the accumulations of 5-ALA-induced PpIX in cancer cells." (PMID 27150264, 2016). "Previous studies have concluded that eEF1A1 has anti-apoptotic functions in cancer cell models but the mechanisms were unclear." (PMID 23799104, 2013). "During our iTRAQ analysis, we identified eEF1A1 to be increased in expression in all of the cancer groups relative to BPH, with relatively higher levels seen in the progressing (+1.8 fold), and metastatic groups (+1.4 fold)." (PMID 22355332, 2012). "Overexpression of EEF1A1 has been related to cell proliferation and cancer development in many tumours including head and neck, breast, leukaemia and hepatocarcinoma." (PMID 22095224, 2012). "The data obtained are an essential step in the move towards an understanding of the functional divergence of the near-identical eEF1A1 and eEF1A2 isoforms, and in particular, the cancer-related properties of the latter." (PMID 18221514, 2008).
cancer (continued). "There is one report showing that ubiquitin-like protein FAT10 could stabilize eEF1A1 and promote cancer cell proliferation." (PMID 39962586, 2025). "First, their differential expression patterns, with eEF1A1 being ubiquitously expressed and eEF1A2 restricted to neurons, muscle, and more frequently overexpressed in cancers, suggest that isoform-specific inhibitors could achieve better therapeutic windows." (PMID 40806463, 2025). "eEF1A1 has been shown to be highly expressed in various cancers." (PMID 39962586, 2025). "In this regard, dual targeting of both EEF1A isoforms could also be considered, since targeting of EEF1A1 isoform has also shown promising results in certain cancers such as HCC." (PMID 38172654, 2024). "Transcript levels of EEF1A1 remained constant in normal and carcinoma cell lines." (PMID 38172654, 2024). "Meanwhile Human HLA‐F adjacent transcript 10 could antagonize its ubiquitination to promote eEF1A1 stabilize and induce cancer cell proliferation." (PMID 35607944, 2023). "We also found an mRNA level increase in EEF1A1 expression in LIHC cancer cells." (PMID 36189258, 2022). "However, the correlations among the levels of PDK3 and EEF1A1, cell apoptosis, and cancer progression in UC require further analysis." (PMID 34589439, 2021). "The persistent activation of the tTA under the constitutively active Eef1a1 locus might be particularly well suited to study the onset and progression of cancer in mice." (PMID 31937792, 2020). "Even in the same cancer, EEF1A1 may act in an opposing manner with respect to different subtypes or stages." (PMID 31703307, 2019). "Keeping these lacunae in hindsight, we have undertaken a pan-cancer approach for comprehensive analysis of expression levels of seven elongation factors namely, EEF1A1, EEF1A2, EEF1B2, EEF1G, EEF1D, EEF1E1 and EEF2, using publicly available databases (Oncomine and TCGA)." (PMID 29342219, 2018). "Moreover, our study has demonstrated that the eEF1A1-PpIX interactions were present in cancer cells and led to the accumulation of ALA-induced PpIX by preventing PpIX degradation." (PMID 27150264, 2016). "Furthermore, the accumulation of PpIX is correlated with eEF1A1 expression, which has provided new insights in both the mechanism of PpIX accumulation in cancer cells in 5-ALA based PDT as well as how the PDT works (target)." (PMID 27150264, 2016). "Microscopy imaging showed that ALA-induced PpIX was co-localized with eEF1A1 in cancer cells." (PMID 27150264, 2016). "Previous studies have demonstrated that eEF1A1 has translation-independent roles in cancer." (PMID 23799104, 2013). "One of the candidates identified as being significantly up-regulated in cancer groups was eukaryotic translation elongation factor 1 alpha 1 (eEF1A1), and was further investigated by immunohistochemistry using prostate tissue samples from localized and metastatic cases." (PMID 22355332, 2012). "Additionally, seven proteins: Cacna1c, Vcl, Fcgbp, Mmp19, Lyz2, Eef1a1, and Gapdhs had cancer-only peptides." (PMID 19936259, 2009). "EEF1A1 may be a valuable prognostic biomarker and promising therapeutic target for many cancers." (PMID 37328464, 2023). "Additionally, N1/N2/N3 tumors, for which cancer cells have been detected in at least one axillary and/or other nearby lymph node, showed significantly lower EEF1A1 mRNA expression compared to N0 tumors from lymph node-negative patients (p < 0.05, Mann-Whitney U test)." (PMID 30224719, 2018). "By adjusting transcriptional yield to translational needs, eEF1A1 renders HSR rapid, robust, and highly selective; thus, representing an attractive therapeutic target for numerous conditions associated with disrupted protein homeostasis, ranging from neurodegeneration to cancer." (PMID 25233275, 2014).